SEMA5A (semaphorin 5A)
Diseases named in the same sentence as SEMA5A in open-access papers (continued):
Sharing a sentence is not in itself a finding about the gene and the disease.
pancreatic cancer (continued). "On the contrary, Sema5A was reported to promote invasion/metastasis in gastric cancer through activation of metalloprotease-9 (MMP-9) and urokinase-type plasminogen activator, and to increase pancreatic cancer metastasis via the Met receptor tyrosine kinase or the MEK/ERK pathway." (PMID 30454024, 2018).
gastric cancer (10 papers, 2012 to 2022). A primary or metastatic malignant neoplasm involving the stomach. "The expression of semaphorin 5A (Sema5A) and its receptor plexin-B3 was shown to be associated with the aggressive nature of pancreatic, prostate, and gastric cancers." (PMID 23050142, 2012). "Another study revealed the SEMA5A important role in metastasis and invasion of gastric cancer cells by uPA regulatory activity and the PI3K/Akt pathway." (PMID 34054953, 2021). "We also confirmed the ability of miR-204 to target Bcl-2, as previously reported in gastric cancer, thus corroborating the correlation between Bcl-2 and Sema5A expression, initially observed in Bcl-2 overexpressing clones." (PMID 30454024, 2018). "In addition, the overexpression of Sema5A and plexin-B3 in gastric carcinoma have been shown to correlate with the invasion and metastasis of tumors." (PMID 25780417, 2015). "Our observations are supported by a study of samples from gastric carcinoma patients illustrating elated expression levels of both SEMA5A and its receptor Plexin-B3 in primary gastric carcinoma and lymph node metastasis in comparison to the non-neoplastic tissue." (PMID 29464045, 2018).
melanoma (9 papers, 2016 to 2023). A malignant, usually aggressive tumor composed of atypical, neoplastic melanocytes. "We further investigated the potential role of Sema5A on VM, a process that reflects the plasticity of aggressive melanoma cells by forming de novo vascular networks and is associated with the malignant phenotype and poor clinical outcome." (PMID 30454024, 2018). "We also focused on the functional relation between Sema5A and Bcl-2, an anti-apoptotic protein associated with melanoma progression, resistance to apoptosis and poor prognosis." (PMID 30454024, 2018). "Here we investigated the role of Semaphorin 5A (Sema5A) on the properties associated with melanoma progression and the factors involved in Sema5A regulation." (PMID 30454024, 2018). "As Bcl-2 protein plays a relevant role in melanoma, being associated with melanoma progression, resistance to apoptosis and poor prognosis, we investigated the effect of Bcl-2 modulation on Sema5A expression." (PMID 30454024, 2018). "A more recent study also identified miR-155-5p and miR-205-5 as possible regulators of Sema5A in melanoma models." (PMID 33858502, 2021). "Sema5A expression was controlled by the transcription factor c-Myb, and if miR-204 overexpression was induced in melanoma cell lines, a concomitant decrease of Sema5A, Bcl-2, and c-Myb protein expression was observed." (PMID 32185171, 2020). "Since little is known regarding the role of Sema5A in melanoma, except for its detection in membrane preparations, we evaluated Sema5A expression in melanoma, by analysing the gene expression profiles." (PMID 30454024, 2018). "To further investigate the role of c-Myb in the regulation of Sema5A, we used A375 melanoma cells transduced with a lentiviral vector for doxycycline-inducible c-Myb silencing." (PMID 30454024, 2018). "The aim of this study was to investigate the role of Sema5A, in melanoma progression and to dissect the molecular mechanisms regulating its expression." (PMID 30454024, 2018). "Bcl-2 forced expression in different melanoma models led to increased level of both Sema5A mRNA and protein." (PMID 30454024, 2018). "Overall, our findings show that Sema5A promotes the in vitro migration and invasion of melanoma cells through Akt/ERK phosphorylation, increasing also VM." (PMID 30454024, 2018). "A significant correlation of Sema5A mRNA expression and melanoma progression was observed by analyzing GEO profile dataset." (PMID 30454024, 2018). "Endogenous Sema5A protein was detected in 95% of human melanoma cell lines tested, in 70% of metastatic specimens from patients affected by melanoma, and 16% of in situ melanoma specimens showed a focal positivity." (PMID 30454024, 2018). "In this study, we investigated the role of Sema5A in melanoma progression, and the molecular mechanism regulating its expression." (PMID 30454024, 2018). "Overall our data provide evidences supporting the role of Sema5A in melanoma progression and the involvement of Bcl-2, miR-204 and c-Myb in regulating its expression." (PMID 30454024, 2018). "We also evaluated the expression of Sema5A protein by immunohistochemistry (IHC) in metastatic lesions from 13 patients with melanoma, finding 70% of positive specimens." (PMID 30454024, 2018). "The relevance of Sema5A in melanoma progression was also furnished by public database of microarray profiling and by analysis of human melanoma specimens, indicating higher level of Sema5A in more aggressive melanoma, and focal positivity in few cases of in situ melanoma." (PMID 33858502, 2021). "In agreement with previously published results obtained in gastric and pancreatic cancer, in 2018 we provided evidence supporting a positive role of Sema5A in melanoma migration and invasion, through Akt/ERK phosphorylation, and in the formation of vasculogenic structures." (PMID 33858502, 2021).
melanoma (continued). "In this paper, we evidence Sema5A expression in metastatic specimens from melanoma patients, and we show that Sema5A expression modulates in vitro melanoma cell migration and invasion, activates the Akt/ERK pathway and is regulated by Bcl-2 and the miR-204/c-Myb axis." (PMID 30454024, 2018). "The observed high acetylation level of the Sema5A promoter region containing the Myb binding site, and the decrement of Sema5A protein level observed after c-Myb knockdown in A375 melanoma cells and in BV173 CML-lymphoid blast crisis cells, confirmed the c-Myb dependent expression of Sema5A." (PMID 30454024, 2018). "Interestingly, we found a higher level of c-Myb at both mRNA and protein levels in Bcl-2 overexpressing melanoma cells, and in accordance with this result, the recruitment of the c-Myb protein at the Sema5A promoter was enhanced by Bcl-2 forced expression." (PMID 30454024, 2018). "Finally, a concomitant decrease in the expression of Sema5A, Bcl-2 and c-Myb proteins was observed in melanoma cells after miR-204 overexpression." (PMID 30454024, 2018). "ACSL3 was coexpressed with SNUPN, TRIP13, and SEMA5A in melanoma." (PMID 27171439, 2016). "Finally, semaphorin 5A is known to regulate melanoma cell migration and invasion, and angiogenesis." (PMID 36831440, 2023). "Moreover, Sema5A silencing confirmed the role of Sema5A in melanoma cell migration and invasion." (PMID 30454024, 2018). "By using M14 and A375SM-SC1 melanoma cell lines and their derivatives stably overexpressing wild-type Bcl-2, we evaluated whether Bcl-2, a protein involved in melanoma progression, resistance to apoptosis, and poor prognosis, plays a role in the regulation of Sema5A expression." (PMID 30454024, 2018). "Thus, Sema5A could represent a potential target for the treatment of melanoma." (PMID 30454024, 2018). "In particular, amplification of SEMA5A and SEMA6A loci (found in 20% and 30% of the melanoma, respectively) were consistent with their increased mRNA expression in melanomas compared to nevi." (PMID 27095580, 2016). "We focused our study on the poorly investigated Sema5A because, to the best of our knowledge, no data have been published yet on its expression and/or function in melanoma, but also because of its controversial role in cancer." (PMID 30454024, 2018). "Treatment of ECD-Sema5A-transfected melanoma cells with Trametinib, a specific MEK inhibitor used for melanoma therapy, significantly reduced the ability of Sema5A- overexpressing cells to migrate, thus indicating that Sema5A-dependent cellular migration is mediated by activation of MEK pathway." (PMID 30454024, 2018).
Intellectual disability (6 papers, 2016 to 2025). "The increased elongation phenotypes observed in ASD and intellectual disability (ID)-associated Semaphorin-5A (Sema5A) Arg676-to-Cys [p.R676C] were also mediated by Dock5 signalosome molecules." (PMID 38666924, 2024). "SEMA5A is also implicated in the Cri-du-chat syndrome in which deletion of the short arm of chromosome 5 (5p-) is associated with phenotypic features, including dysmorphic facial features, microcephaly, and intellectual disability." (PMID 33578652, 2021).
glioblastoma (4 papers, 2012 to 2022). The most malignant astrocytic tumor (WHO grade IV). "On the other hand in glioblastoma, loss of SEMA5A leads to Rac1 activation resulting in increased invasiveness, indicating that SEMA5A suppresses motility of cell." (PMID 30577767, 2018). "Taken together, these findings suggest a tumor suppressor role of Sema5A, which is compromised towards high-grade glioblastomas." (PMID 23050142, 2012). "However, in contrast to our findings, SEMA5A acting as a ligand through Plexin-B3 receptor impedes cellular motility in glioblastoma patients." (PMID 29464045, 2018). "Notably, stimulation of human glioblastoma cells with Sema5A promotes their differentiation from anaplastic to astrocytic morphology, which is reminiscent of the less pleomorphic and well-differentiated features associated with low-grade astrocytomas." (PMID 23050142, 2012).
rheumatoid arthritis (4 papers, 2015 to 2025). A chronic, systemic autoimmune disorder characterized by inflammation in the synovial membranes and articular surfaces. "Intriguingly, research in rheumatoid arthritis (RA) has revealed that Semaphorin 5A in RA synovial fluid curtails ferroptosis in RA synovial fibroblasts by tweaking the PI3K/AKT/mTOR axis to boost GPX4 levels." (PMID 40586853, 2025).
breast carcinoma (3 papers, 2018 to 2022). "In contrast with SEMA5A, other semaphorins like Semaphorin 7A in breast cancer cells and Semaphorin 3E through PlexinD1 axis in ovarian cancer cells are known to mediate EMT." (PMID 30577767, 2018). "Thus, we hypothesized that the tumor Plexin B3-neuron Sema5A interaction mediates sensory nerve-driven breast cancer cell migration." (PMID 36333352, 2022).
lung carcinoma (3 papers, 2011 to 2025). "For instance, both the most negatively correlated gene, RTN1, involved in detoxification in lung cancer, and a potential lung cancer tumor suppressor, SEMA5A, were significantly down-regulated though frequently amplified in tumor tissues." (PMID 21935476, 2011). "A similar association with lung cancer among nonsmokers was reported for SEMA5A; however, poor survival among nonsmoking women with NSCLC was related to transcriptional and translational downregulation of SEMA5A in cancer tissue." (PMID 38067240, 2023).
lymph node metastasis (3 papers, 2018 to 2021). "One of the predicted targets of miR-203a in our analysis was Semaphorin 5a that is associated with lymph node metastasis and adverse prognosis." (PMID 34316330, 2021). "SEMA5A high expression patients were more likely than low expression patients to have lymph node metastasis (P < 0.001)." (PMID 29977159, 2018). "Another interesting observation in human PC patients was the downregulation of SEMA5A expression in lymph node metastasis." (PMID 29464045, 2018). "In contrast, SEMA5A mRNA expression was down-regulated in lymph node metastasis, and we observed no change of SEMA5A expression in patients negative for metastasis." (PMID 29464045, 2018).
cervical cancer (2 papers, 2018 to 2021). A primary or metastatic malignant neoplasm involving the cervix. "Sema5A overexpression was significantly associated with lymphangiogenesis, poor prognosis, and the metastatic potential of cervical cancer cells." (PMID 33537086, 2021). "SEMA5A overexpression was also significantly associated with lymphangiogenesis, poor prognosis, and the metastatic potential of cervical cancer cells." (PMID 29977159, 2018). "In contrast, our survival data provide compelling evidence that SEMA5A overexpression is associated with unfavorable outcome in cervical cancer." (PMID 29977159, 2018). "Further studies are needed to fully understand the underlying molecular pathways of SEMA5A in cervical cancer." (PMID 29977159, 2018). "Our results substantiate that SEMA5A is associated with LNM in cervical cancer." (PMID 29977159, 2018). "Sema5A, has also been identified as a novel proangiogenic molecule with elevated expression in stage IIb cervical cancer, compared to earlier stages." (PMID 33537086, 2021). "Semaphorin 5A also increased cervical cancer cell invasion by stimulating the expression and activity of matrix metalloproteinase-2 and matrix metalloproteinase-9 via PI3K/AKT and plexin-B3." (PMID 29977159, 2018). "We performed western blots for SEMA5A using protein lysates collected from in Hela, Siha, and Caski cervical cancer cells." (PMID 29977159, 2018). "Our aim is to investigate the prognostic value of semaphorin 5A and its potential role in lymphangiogenesis and invasion in cervical cancer." (PMID 29977159, 2018). "We suggest that SEMA5A expression mainly plays a role in cervical cancer development at the primary site." (PMID 29977159, 2018). "Our findings indicate that the proinvasive activity of SEMA5A is associated with the induction of MMP-2 and MMP-9 in HeLa cervical cancer cells." (PMID 29977159, 2018). "In the present study, we attempted to elucidate the role of SEMA5A in cervical cancer by correlating its expression with clinicopathological features and prognosis." (PMID 29977159, 2018). "In present study, SEMA5A expression was elevated in stage IIb cervical cancer tissues compared with stage Ia, Ib, and IIa cervical cancer tissues." (PMID 29977159, 2018). "In vitro, we determined the role and mechanistic pathways of semaphorin 5A in tumor progression in cervical carcinoma cell lines." (PMID 29977159, 2018). "Importantly, the association between Sema5A and lymph node metastasis (LNM) in cervical cancer has been linked to three mechanisms." (PMID 33537086, 2021). "However, our findings from cervical cancer patients suggested that SEMA5A was likely involved in the lymphangiogenesis and capacity of cervical cancer cells to metastasize to the lymph nodes." (PMID 29977159, 2018). "In present study, we demonstrated that SEMA5A contributes to cervical cancer cell invasion." (PMID 29977159, 2018). "The constitutive expression of SEMA5A protein differed according to cervical cancer stage." (PMID 29977159, 2018). "Of the 232 cervical cancer patients, 123 patients had high SEMA5A expression." (PMID 29977159, 2018). "Thus, we evaluated SEMA5A expression and its association with lymphangiogenesis, LNM, histopathological characteristics, and survival patterns in patients with cervical cancer." (PMID 29977159, 2018). "The MMP inhibitor GM6001 reduced the ability of SEMA5A to stimulate cervical cancer cell invasion." (PMID 29977159, 2018). "Our findings indicate that semaphorin 5A may represent a poor prognostic biomarker and anti-metastasis therapeutic target in cervical cancer." (PMID 29977159, 2018). "Our results indicate that SEMA5A is prognostic indicator in cervical cancer." (PMID 29977159, 2018). "Therefore, Sema5A is considered a prognostic indicator in cervical cancer." (PMID 33537086, 2021). "Second, Sema5A induces MMP-2 and MMP-9 that mediate the invasive behavior of cervical cancer cells, which involves PlexinB3 receptor and the intracellular PI3K/AKT pathway." (PMID 33537086, 2021).
cervical cancer (continued). "This study demonstrated for the first time a link between SEMA5A overexpression and lymphangiogenesis, LNM, and reduced survival in cervical cancer patients." (PMID 29977159, 2018). "Second, SEMA5A stimulates MMP-2 and MMP-9 to increase the invasive potential of cervical cancer cells." (PMID 29977159, 2018). "Although we found that high-expression of SEMA5A may accelerate LNM and progression of cervical cancer, the limitations of the study should be noted." (PMID 29977159, 2018). "However, the role of semaphorin 5A in cervical cancer is not known." (PMID 29977159, 2018). "However, SEMA5A expression and its correlation with lymphangiogenesis, LNM, and clinicopathological parameters in cervical cancer have not been reported." (PMID 29977159, 2018). "However, the functional role of SEMA5A in tumor progression, lymphangiogenesis, and LNM in cervical cancer has not been reported." (PMID 29977159, 2018).
diabetic neuropathy (2 papers, 2021 to 2023). A chronic, pathological complication associated with diabetes mellitus, where nerve damages are incurred due to diabetic microvascular injury involving small blood vessels that supply these nerves, resulting in peripheral and/or autonomic nerve dysfunction. "Additionally, SEMA5A could play a role in chemotherapy-induced peripheral neuropathy (CIPN) given that it is important in the guidance of axons in the central and peripheral nervous system and also that semaphorins are involved in diabetic neuropathy." (PMID 33578652, 2021).
lung adenocarcinoma (2 papers, 2021 to 2023). A carcinoma that arises from the lung and is characterized by the presence of malignant glandular epithelial cells. "The downregulation of SEMA5A in lung adenocarcinoma tissues was associated with a poor overall survival." (PMID 36793597, 2023). "Sema5A downregulation in lung adenocarcinoma tissues was associated with poor overall survival." (PMID 33537086, 2021). "A suppressive role for SEMA5A in lung adenocarcinoma involves the inhibition of the proliferation and migration of lung transformed cells." (PMID 36793597, 2023). "Furthermore, since transmembrane Sema5A can be cleaved by ADAM17 metalloproteases, this mechanism contributes to the downregulation of surface‐exposed Sema5A in lung adenocarcinoma cells." (PMID 33537086, 2021).
mastitis (2 papers, 2012 to 2025). Inflammation of breast tissue during lactation or postpartum due to an obstructed duct or infection. "Because 12GFEZL promotes greater semaphorin 5A expression than 13GFEZL, the susceptibility to mastitis might result from differences in immune response." (PMID 22973545, 2012). "These included genes and QTLs related to somatic cell count and mastitis (CACNA2D1, SEMA5A, NEGR1, PTK2B, CTNNA3), gastrointestinal parasites (PTK2B), and various viral or bacterial diseases." (PMID 41273432, 2025). "When cows are infected with mastitis, FEZL induces tumor necrosis factor-α and interleukin-8 through enhancing semaphorin 5A." (PMID 22973545, 2012).
microcephaly (2 papers, 2018 to 2021). A congenital or acquired developmental disorder in which the circumference of the head is smaller than normal for the person's age and sex. "The derivative chromosome results in a partial monosomy of 5p15.2 → pter, producing haploinsufficiency of the SDHA (5p15.33) and SEMA5A (5p15.31) genes that have been related to psychomotor retardation, microcephaly, pachygyria and microgyria." (PMID 29760780, 2018).
Alzheimer disease (1 paper, 2024). A progressive, neurodegenerative disease characterized by loss of function and death of nerve cells in several areas of the brain leading to loss of cognitive function such as memory and language. "Additionally, Sema5A and/or Sema7A are involved in the regulation of neurogenesis in adults, and dysfunction is also associated with Alzheimer’s disease-like phenotypes." (PMID 38666924, 2024).